RNU7-79P (RNA, U7 small nuclear 79 pseudogene)
Synonyms: U7.79
Gene: Small nuclear RNA gene on chromosome 15 (85,389,823 to 85,389,884, reverse strand). Ensembl gene ENSG00000251891.
Homologues: Orthologues: chimpanzee U7 (98% identical), macaque U7 (94% identical), dog U7 (69% identical). Paralogues in human: RNU7-80P (90% identical), U7 (87% identical), RNU7-11P (84% identical), RNU7-2P (84% identical), RNU7-48P (84% identical), RNU7-55P (84% identical), RNU7-59P (84% identical), RNU7-84P (84% identical), RNU7-9P (84% identical), RNU7-120P (82% identical), RNU7-140P (82% identical), RNU7-26P (82% identical), and 142 more.